IRF3 (interferon regulatory factor 3)
Diseases named in the same sentence as IRF3 in open-access papers (continued):
Sharing a sentence is not in itself a finding about the gene and the disease.
myocarditis (3 papers, 2018 to 2023). Myocarditis is a condition that is characterized by inflammation of the heart muscle (myocardium). "When we compared the openness of genomic regions predicted to be the sites of IRF3/7 binding, chromatin accessibility was reduced in myocarditis CD8 effector and cytotoxic NK cells." (PMID 37264110, 2023). "Consistent with the downregulation of motif activities of IRF3 and IRF7, peripheral immune cells showed a reduced motif activity level of STAT1::STAT2 and IRF9 at the time of myocarditis." (PMID 37264110, 2023). "In our datasets, although the gene activity and RNA expression level of IRF3 showed minimal changes, the motif activity of IRF3 and IRF7 was decreased at myocarditis state across all cell subpopulations except for pDCs and memory B cells." (PMID 37264110, 2023). "In contrast to these findings, Irf3 displayed no significant changes during acute or chronic myocarditis." (PMID 29538462, 2018). "Similarly, IFN regulatory factor 3 (IRF3) is required for induction of IFN-β in primary cardiac myocytes, and mice lacking IRF3 develop severe myocarditis." (PMID 34237110, 2021).
non-alcoholic fatty liver disease (3 papers, 2023 to 2025). "The involvement of bile duct cells in the development of nonalcoholic fatty liver disease was reported; however, they did not study IRF3 expression but cellular senescence markers and chemokines." (PMID 37511764, 2023).
schizophrenia (3 papers, 2023 to 2024). A major psychotic disorder characterized by abnormalities in the perception or expression of reality. "Six candidate genes (SFN, KDM5B, MYLK, IRF3, IRF7, and ID1) were identified with diagnostic significance for schizophrenia." (PMID 37113536, 2023). "Furthermore, we established a schizophrenia diagnostic model based on genes associated with cellular senescence, which contain 6 candidate genes (SFN, KDM5B, MYLK, IRF3, IRF7, ID1)." (PMID 37113536, 2023).
triple-negative breast carcinoma (3 papers, 2022 to 2024). An invasive breast carcinoma which is negative for expression of estrogen receptor (ER), progesterone receptor (PR), and human epidermal growth factor receptor 2 (HER2). "For instance, PTEN-null triple-negative breast cancer (TNBC) cell lines were hyper-responsive to STING agonists because of diminished STING turnover and increased production of IRF3 targets." (PMID 38214828, 2024). "Microtubule destabilizers have been shown to activate stimulator of interferon genes (STING)-interferon regulatory factor 3 (IRF3) dependent production of IFN-β and downstream interferon-stimulated genes (ISGs) in both immune and triple negative breast cancer cells." (PMID 37333411, 2023).
acute pancreatitis (2 papers, 2024 to 2025). An acute inflammatory process that leads to necrosis of the pancreatic parenchyma. "In acute pancreatitis (AP), STING deficiency attenuates NLRP3-mediated macrophage pyroptosis, reduces IRF7 expression, and disrupts the nuclear translocation of phosphorylated IRF3 (p-IRF3)." (PMID 41153813, 2025).
allergic asthma (2 papers, 2019 to 2025). A asthma with a basis in a pathological type I hypersensitivity reaction. "STING/TBK1/IRF3 axis and IL-33 signaling, required for cGAMP-induced allergic inflammation, may be novel therapeutic targets for allergic asthma." (PMID 31616416, 2019). "Furthermore, several studies concerning the direct sensitization of HDM have indicated that various factors, such as IL-21 from CD4+ T cells, IL-33 from inflammatory monocytes, TLR4-dependent inflammation, and IRF3 signals, participate in mouse models of allergic asthma." (PMID 31616416, 2019). "Thus, cGAMP functions as a type 2 adjuvant in the lung and can promote allergic asthma in manners that dependent on the intracellular STING/TBK1/IRF3/7 signaling pathway and the resultant intercellular signaling pathway via IL-33 and ST2 might be a novel therapeutic target for allergic asthma." (PMID 31616416, 2019).
ANCA-associated vasculitis (2 papers, 2024 to 2025). "In the same line it was published that the progression of ANCA-associated vasculitis is dependent on the activation of cGAS/STING/IRF3 axis." (PMID 40111902, 2025).
arenavirus infection (2 papers, 2017 to 2023). "Together with our own data, these findings collectively suggest that the impact of ExoN activity on NP-mediated antagonism of IFN-I responses during arenavirus infection has been significantly overestimated, and rather IRF3 inhibition may play a predominant role." (PMID 36603036, 2023). "LCMV infection failed to suppress tumour growth in Irf3−/−xIrf7−/− mice, supporting the functional importance of IFN-I for the antitumour effect of arenavirus infection." (PMID 28248314, 2017).
breast invasive carcinoma (2 papers, 2024 to 2025). "Specifically, DDX58, C6orf150, IKBKE, TBK1, and IRF3 exhibited a pronounced increase in breast invasive carcinoma (BRCA), while MAVS and TMEM173 expression was significantly lower in BRCA compared to normal controls." (PMID 38817870, 2024).
Burkitt lymphoma (2 papers, 2014 to 2017). A rare form of malignant mature B-cell non-Hodgkin lymphoma. "Furthermore, EBERs induce IL-10 expression through IRF3, but not NF-κB activation, in BL (Burkitt's lymphoma) cells, suggesting that EBER acts as an autocrine growth factor in BL cells." (PMID 28603696, 2017). "Furthermore, EBERs induce interleukin-10, an autocrine growth factor for Burkitt’s lymphoma cells, by activating RIG-I/interferon regulatory factor 3 pathway, suggesting that EBER-mediated innate immune signaling modulation contributes to EBV-mediated oncogenesis." (PMID 25101570, 2014).
chlamydial infection (2 papers, 2015 to 2022). "By contrast, TLR3-mediated sensing of chlamydial infection in human Sertoli cells did not elicit the activation of the related pathways, namely NFkB and IRF3, as well as the subsequent cytokine production." (PMID 35174109, 2022).
cholangiocarcinoma (2 papers, 2024 to 2026). A carcinoma that arises from the intrahepatic biliary tree (intrahepatic cholangiocarcinoma) or from the junction, or adjacent to the junction, of the right and left hepatic ducts (hilar cholangiocarcinoma). "The results indicate a significant upregulation of IKKε (encoding gene IKBKE) and TBK1 expression but a decrease in IRF3 expression within the intrahepatic cholangiocarcinoma metastasis group." (PMID 38817870, 2024). "Tissue samples from the HPA database were analyzed to determine the functions of DDX58, MAVS, C6orf150, TMEM173, IKBKE, TBK1, and IRF3 in cholangiocarcinoma cells." (PMID 38817870, 2024). "To gain a deeper understanding of the relevance and underlying mechanisms of the innate immune pathway in cholangiocarcinoma, we investigated the expression levels of DDX58, MAVS, C6orf150, TMEM173, IKBKE, TBK1, and IRF3 in different cell types using the TISCH2 database." (PMID 38817870, 2024). "Immunohistochemical results revealed that the expression of RIG-I, MAVS, cGAS, IRF3, MDA5, IFIT2, and IRF7 was significantly higher in liver tissue slices from patients with cholangiocarcinoma than in the control group." (PMID 38817870, 2024).
colon adenocarcinoma (2 papers, 2022 to 2024). "Moreover, IRF3 and IRF7 were linked to a poor prognosis in colon adenocarcinoma." (PMID 35012444, 2022).
dermatitis (2 papers, 2023). An inflammatory process affecting the skin. "Second, STING agonism increases spinal STING-dependent phosphorylation of TBK1 and IRF3 in morphine-induced acute itch and dermatitis-induced chronic itch." (PMID 37122031, 2023). "Phenome-wide Mendelian randomization on 525 disease traits revealed that IRF3 and POSTN were associated with skin disorders, such as malignant neoplasm of skin and residual hemorrhoidal skin tags." (PMID 37404740, 2023).
E. coli infection (2 papers, 2010 to 2024). "IRF3 inactivation leads to the overexpression of IRF7, exacerbating kidney pathology in E. coli infections." (PMID 39166412, 2024). "The results suggest that Irf3 is essential for a functioning innate immune defense against UTI, to maintain tissue integrity and to clear mucosal E. coli infection." (PMID 20886096, 2010).
endometrial cancer (2 papers, 2024 to 2026). Primary or metastatic malignant neoplasm involving the endometrium (mucous membrane that lines the endometrial cavity). "Given the effector roles of phosphorylated TBK1 and IRF3, AZD1775 was shown to activate the innate immune response signaling pathway in endometrial cancer cell lines." (PMID 38169513, 2024). "Western blotting assay found that in five endometrial cancer cell lines, compared to the control group, AZD1775 treatment did not significantly alter the expression of total TBK1 and IRF3, but notably upregulated the expression of pTBK1 and pIRF3." (PMID 38169513, 2024). "While the overall levels of TBK1 and IRF3 in HEC-1-A and HEC-1-B endometrial cancer cell lines did not change significantly, the expression levels of pTBK1 and pIRF3 increased." (PMID 38169513, 2024).
eosinophilia (2 papers, 2009 to 2013). "Following the OVA challenge, the augmentation of eosinophilia in BALF was restored not only in the mice reconstituted with BMMCs from wild-type mice but also in those with BMMCs from TRIF−/−mice or IRF-3−/−mice." (PMID 23452625, 2013). "However, the augmentation of airway eosinophilia was restored in the mice reconstituted with BMMCs from TRIF−/−mice or IRF-3−/−mice." (PMID 23452625, 2013). "In wild-type mice and IPS-1−/−mice, the poly IC treatment significantly augmented the eosinophilia in BALF, but it did not in TRIF−/−mice or IRF-3−/−mice, suggesting that the TRIF-IRF-3 pathway is essential for the poly IC-induced augmentation of airway eosinophilia." (PMID 23452625, 2013).
epilepsy (2 papers, 2025). A brain disorder characterized by episodes of abnormally increased neuronal discharge resulting in transient episodes of sensory or motor neurological dysfunction, or psychic dysfunction. "Furthermore, the mRNA levels of Irf3, Tlr4, Myd88, and Irak4 genes—encoding innate immune system markers essential for maintaining neuronal excitation/inhibition balance and implicated in epilepsy—were examined." (PMID 40608247, 2025). "Reduced IRF3 signaling could contribute to an environment conducive to neurodegeneration, impaired neurogenesis, and dysfunctional synaptic remodeling, further enhancing the progression of seizures and epilepsy-related changes in the brain." (PMID 40217352, 2025).
Fever (2 papers, 2017 to 2019). Body temperature elevated above the normal range. "Exogenous pathogens activate the TLRs signaling pathway constituents such as TLR4, MyD88, TBK1, IRF3, and IRAK4, and subsequently stimulate the release of pro-inflammatory cytokines which promote to progress a disease by producing fever and tissue damage." (PMID 28489052, 2017). "The OROV fever pathogenesis was in fact described as restricted by the IFN pathway-related signaling molecules MAVS, IRF-3, IRF-7 in non-myeloid cells." (PMID 31784575, 2019).
fibrosarcoma (2 papers, 2015 to 2022). A malignant mesenchymal fibroblastic neoplasm affecting the soft tissue and bone. "In fibrosarcoma cells, IRF3 and IRF7 mRNAs were detected, while IRF1 and MyD88 mRNAs were regulated." (PMID 35737804, 2022). "The same IRF-3-dependent mechanism of poly I:C-induced apoptosis is effective also in human fibrosarcoma cells." (PMID 25444175, 2015).
fibrosis (2 papers, 2018 to 2024). the formation of excess fibrous connective tissue in an organ or tissue in a reparative or reactive process. "For instance, livers from fibrosis patients show increased IRF3 expression and nuclear translocation in hepatocytes when compared to those from healthy volunteers." (PMID 38233853, 2024).
head and neck squamous cell carcinoma (2 papers, 2022 to 2025). A squamous cell carcinoma that arises from any of the following anatomic sites: lip and oral cavity, nasal cavity, paranasal sinuses, pharynx, larynx, and salivary glands. "Specifically, in head and neck squamous cell carcinoma (HNSCC), the overexpression of ALKBH5 suppresses RIG‐I‐mediated IFNα secretion via the IκB kinase epsilon/TBK1/interferon regulatory factor 3 (IRF3) signaling pathway, which is closely related to tumor cell programmed cell death." (PMID 39802639, 2025).
infarction (2 papers, 2018 to 2025). A localised pathological necrosis of tissue resulting from obstruction of the blood supply usually by a thrombus, an embolus, or vascular torsion. "The complete rescue of postmyocardial infarction mortality upon deletion of Irf3 or Ifar is rather unexpected given the multifarity of the involved mechanism in postmyocardial infarction death and the partial role of the innate immune response." (PMID 40180542, 2025). "Collectively, the data point to the prominent role of the IRF3 and its receptors in the pathogenesis of cardiac remodeling postmyocardial infarction." (PMID 40180542, 2025). "Both systemic and myocyte-specific deletion of the Irf3 gene in mice afford protective effects against cardiac remodeling and death postmyocardial infarction (coronary ligation)." (PMID 40180542, 2025). "Moreover, Irf3 and Irf7 showed also an increased gene expression 5 days after infarction in the scar tissue." (PMID 29538462, 2018).
ischemia (2 papers, 2014 to 2016). A hypoperfusion of the BLOOD through an organ or tissue caused by a PATHOLOGIC CONSTRICTION or obstruction of its BLOOD VESSELS, or an absence of BLOOD CIRCULATION. "IRF3 participates in the immune liver injury induced by HCV infection and plays an important role in the development of alcoholic liver injury and ischemia/reperfusion liver injury." (PMID 27448985, 2016).
lung squamous cell carcinoma (2 papers, 2024 to 2025). "Silencing of RFWD3 in lung squamous cell carcinoma (LUSC) H2170 cells also led to upregulation of p‐STING, p‐TBK1, p‐IRF3, and p‐STAT1." (PMID 41117130, 2025).
lymphoma (2 papers, 2014 to 2021). A malignant (clonal) proliferation of B- lymphocytes or T- lymphocytes which involves the lymph nodes, bone marrow and/or extranodal sites. "STING enhances the formation of a complex of IRF3-Bax leading to adult T-cell leukemia/lymphoma apoptosis, suggesting that STING is responsible for anti-tumor activity against adult T-cell leukemia/lymphoma." (PMID 34830754, 2021). "In addition, previous work has observed IRF3, NFκB and RNAPII enriched at L2 in SeV-treated Namalwa Burkitt's Lymphoma cells." (PMID 25348400, 2014).
Myocardial fibrosis (2 papers, 2022 to 2025). "Recent studies have shown that IRF3 is also involved in a wide range of pathophysiological diseases, such as cancer, myocardial fibrosis, metabolic disorders, and so on." (PMID 35037825, 2022).
nasopharyngeal carcinoma (2 papers, 2024 to 2025). A carcinoma arising from the nasopharyngeal epithelium. "For instance, circBART2.2 was found to promote PD-L1 transcription through binding retinoic acid-inducible gene I (RIG-I), activating transcription factors interferon regulatory factor 3 (IRF3) and nuclear factor-kappa B (NF-κB), eventually inducing immune escape of nasopharyngeal carcinoma." (PMID 40158127, 2025).
neurofibromatosis (2 papers, 2022). A hereditary neoplastic syndrome in which tumors grow in the nervous system. "Nucleic acid recognition, through activation of IRF3, is able to induce protein phase separation and the formation of membraneless organelles and can detect NF2m-IRF3 condensates in patients with neurofibromatosis type 2." (PMID 36497453, 2022).
osteoporosis (2 papers, 2018 to 2024). A condition of reduced bone mass, with decreased cortical thickness and a decrease in the number and size of the trabeculae of cancellous bone (but normal chemical composition), resulting in increased fracture incidence. "More importantly, for the first time, we showed the significance of Irf-3 in regulating osteoclastogenesis, providing a novel molecular target for the development of future anti-osteoporosis therapeutic strategies." (PMID 30254586, 2018).
pancreatitis (2 papers, 2024). Inflammation of the pancreas. "IL-33 and IRF3 were highly expressed in the nucleus of epithelial cells in pancreatitis and pancreatitis-associated PDAC samples." (PMID 38816352, 2024). "To extend our findings to cancer-prone chronic inflammation in humans, we examined IL-33 and IRF3 expression in the epithelial cells across 15 matched samples of the normal pancreas, pancreatitis, and pancreatitis-associated pancreatic ductal adenocarcinoma (PDAC)." (PMID 38816352, 2024). "Wip1 aggravates CAE-induced autophagy and inflammatory injury in acinar cells by targeting STING/TBK1/IRF3 in experimental pancreatitis." (PMID 38671352, 2024).
parasite infection (2 papers, 2021 to 2023). "Immunofluorescence images also confirmed that T. gondii infection induced IRF3 nuclear import was dramatically inhibited with PI3K/AKT inhibitors that most of IRF3 was accumulated in the host cytoplasm even with the parasite infection." (PMID 34464509, 2021). "Here, we discover a host gene [Src homology 2-containing inositol phosphatase 1 (SHIP1)] that can regulate IFN-I signaling by modulating NDP52-mediated selective autophagic degradation of IRF3 and significantly affect parasitemia and resistance of Plasmodium-infected mice." (PMID 37366613, 2023). "Downregulation of SHIP1 increases phosphorylation and stability of IRF3 and IFN-I production, leading to improved host antimalarial immunity after N67 parasite infection." (PMID 37366613, 2023).
pulmonary arterial hypertension (2 papers, 2024 to 2025). Pulmonary arterial hypertension (PAH) is a group of diseases characterized by mean pulmonary artery pressure >20 mmHg and elevated pulmonary arterial resistance leading to right heart failure. "System analysis of the human pulmonary arterial hypertension lung transcriptome previously showed an activation signature for several genes in the non‐canonical IKB kinase pathway including TBK1/IKKε, and interferon regulatory factors (IRF3/7)." (PMID 38610069, 2024).
rectal cancer (2 papers, 2017 to 2021). A primary or metastatic malignant neoplasm that affects the rectum. "IRF3 expression in patients with rectal cancer was negatively correlated with the infiltration level of CD8+ T cells, and positively correlated with the infiltration level of CD4+ T cells." (PMID 34488791, 2021). "In particular, the authors demonstrated that the IRF2 mutational status is associated with both colon and rectal cancer, whereas mutations in other genes involved in IFN signaling pathway were uniquely associated with colon (IFN-γ and IRF3) or rectal cancer (IFNGR1, IFNGR2, IRF4, IRF6, and IRF8)." (PMID 28798748, 2017).
renal carcinoma (2 papers, 2021 to 2024). A carcinoma arising from the epithelium of the renal parenchyma or the renal pelvis. "A recent study demonstrated that overexpression of IRF3 predicted poor prognosis in clear cell renal cell carcinoma, indicating that IRF3 could serve as promising prognostic marker and therapeutic target in renal cancer." (PMID 34768716, 2021).
renal fibrosis (2 papers, 2021 to 2025). A final common manifestation of a wide variety of chronic kidney diseases characterized by glomerulosclerosis and tubulointerstitial fibrosis. "In addition, IRF3 drives hypoxia-induced renal fibrosis via upregulation of PFKFB3-dependent glycolysis." (PMID 41208891, 2025). "However, another study using a cisplatin-induced renal fibrosis model showed that STING induced NF-κB expression rather than that of IFN-I in an IRF3-independent manner." (PMID 34484196, 2021).
Salmonella Infections (2 papers, 2021). Infections with bacteria of the genus SALMONELLA. "There had been an interaction between heat stress and Salmonella infection in the expressions of IFN-α, IFN-γ, IRF3, and p-IRF3." (PMID 34061266, 2021).